FAM13A (family with sequence similarity 13 member A)
Diseases named in the same sentence as FAM13A in open-access papers (continued):
Sharing a sentence is not in itself a finding about the gene and the disease.
FAM13A also shares sentences with these, for which no sentence is quoted: atherosclerosis (1 paper); chronic bronchitis (1); Glucose intolerance (1); Hepatic steatosis (1); hepatocellular carcinoma (1); idiopathic interstitial pneumonia (1); metabolic syndrome (1); polycystic kidney disease 2 (1); polycystic liver disease (1); silicosis (1); squamous cell carcinoma (1).